PAQR5 (progestin and adipoQ receptor family member 5)
Description:
Plasma membrane progesterone (P4) receptor coupled to G proteins. Seems to act through a G(i) mediated pathway. May be involved in oocyte maturation.
Synonyms: MPRG; FLJ20190
Tractability: Antibody: UniProt places it where antibodies can reach, with medium confidence; UniProt predicts a signal peptide or a membrane-spanning region; its Gene Ontology location is reachable by antibodies, with medium confidence. PROTAC: ubiquitination databases record sites on it.
Gene: Protein-coding gene on chromosome 15 (69,298,888 to 69,407,780, forward strand). Ensembl gene ENSG00000137819.
Subcellular location: Cell membrane
Subcellular location (Human Protein Atlas): Vesicles
Gene Ontology:
Molecular function: protein binding; signaling receptor activity
Cellular component: membrane; plasma membrane
Genetic constraint (gnomAD): Loss-of-function variants: 15 observed, 29.26 expected, observed/expected ratio (o/e) 0.51, 90% interval 0.34 to 0.79. The upper end of that interval is the gene's LOEUF score, 0.79, which puts it in group 3 of 6, group 1 being the genes least tolerant of losing a copy. Missense variants: 326 observed, 375.55 expected, observed/expected ratio (o/e) 0.87, 90% interval 0.79 to 0.95. Synonymous variants: 110 observed, 141.99 expected, observed/expected ratio (o/e) 0.77, 90% interval 0.66 to 0.91.
Homologues: Orthologues: chimpanzee PAQR5 (98% identical), macaque PAQR5 (97% identical), mouse Paqr5 (92% identical), rat Paqr5 (92% identical), pig PAQR5 (90% identical), dog PAQR5 (86% identical), guinea pig PAQR5 (84% identical), rabbit PAQR5 (62% identical), zebrafish paqr5b (58% identical), tropical clawed frog paqr5 (58% identical), zebrafish paqr5a (52% identical), Caenorhabditis elegans paqr-1 (20% identical), and 2 more. Paralogues in human: PAQR6 (51% identical), PAQR8 (27% identical), PAQR9 (25% identical), PAQR7 (25% identical), ADIPOR2 (22% identical), ADIPOR1 (21% identical), PAQR4 (20% identical), PAQR3 (18% identical), MMD2 (16% identical), MMD (14% identical).
Diseases named in the same sentence as PAQR5 in open-access papers:
PAQR5 is named in the same sentence as 33 diseases in open-access papers, as found by Europe PMC text mining. Sharing a sentence is not in itself a finding about the gene and the disease. The quoted sentences say what the papers report.
endometrial cancer (5 papers, 2020 to 2025). Primary or metastatic malignant neoplasm involving the endometrium (mucous membrane that lines the endometrial cavity). "In human endometrial cancers, increased PAQR5 expression was associated with a favorable patient prognosis, whereas increased PAQR6 expression was associated with a poor prognosis in prostate cancers." (PMID 35127538, 2021). "In contrast, an increased expression of PAQR5/8 genes was associated with a favorable prognosis in endometrial cancers." (PMID 35127538, 2021). "Recent evidence suggests that PAQR5 functions as a prognostic marker and protective factor in esophageal adenocarcinoma, and it plays a significant role in the antitumor activity of progesterone in ovarian and endometrial cancers, where elevated PAQR5 expression correlates with a lower FIGO stage." (PMID 40336138, 2025).
endometriosis (3 papers, 2020 to 2025). The growth of functional endometrial tissue in anatomic sites outside the uterine body. "The analysis of gene expression showed that PAQR7 and PAQR5 expression was lower in both eutopic and ectopic endometrium as compared to the endometrium of women without endometriosis, whereas the expression of PAQR8 and PAQR6 was only reduced in eutopic endometrium." (PMID 32733932, 2020). "The results of the present study showed that both the expression of PAQR7 and PAQR5, as well as the protein content of mPRα and mPRβ, was significantly reduced in the ectopic endometrium of patients with endometriosis compared to the endometrium of women without the disease." (PMID 32733932, 2020). "Using RT-qPCR, we observed that the expression of PAQR7, PAQR8, PAQR5, and PAQR6 genes was significantly downregulated in the eutopic endometrium of patients with endometriosis compared with the endometrium of women without the disease." (PMID 32733932, 2020).
kidney cancer (2 papers, 2021 to 2022). Primary or metastatic malignant neoplasm involving the kidney. "Since the PAQR5 gene is highly expressed in normal kidney tissue, we then focused our assessment on PAQR5 expression in kidney cancers using the RNA-seq dataset from the TCGA project." (PMID 35127538, 2021). "In terms of gender, PAQR5 was significantly less expressed in tumor tissues from male patients than in those from female patients (P < 0.01), consistent with a higher incidence of kidney cancer in men than in women." (PMID 36119517, 2022). "There are no reports on PAQR family members in kidney cancer, and the significance of PAQR5 in kidney renal clear cell carcinoma (KIRC) is not yet known." (PMID 36119517, 2022).
lymph node metastases (2 papers, 2022 to 2025). "For instance, PAQR5 expression inversely correlates with TGF-β signaling, and reduced PAQR5 levels are associated with aggressive clinicopathological features, including advanced stage, high grade, lymph node metastasis, and distant metastasis, in ccRCC." (PMID 40395557, 2025). "Tissues with lymph node metastases showed lower expression of PAQR5 than those without metastases." (PMID 36119517, 2022).
prostate carcinoma (2 papers, 2016 to 2021). A carcinoma that arises from epithelial cells of the prostate gland. "CDHR1 and PAQR5 were the most significantly differential transcripts in prostate cancer and pancreatic cancer patients, respectively." (PMID 26786760, 2016).
renal carcinoma (2 papers, 2022 to 2023). A carcinoma arising from the epithelium of the renal parenchyma or the renal pelvis. "Moreover, renal carcinoma is usually associated with intratumoral fibrosis, and markers of fibrosis such as type I collagen and fibronectin promote tumor progression, suggesting that kidney fibrosis contributes to decreased PAQR5 expression." (PMID 37553369, 2023). "However, the role of PAQR5 in renal carcinoma remains unclear." (PMID 36119517, 2022).
Ureteral obstruction (2 papers, 2023 to 2024). Obstruction of the flow of urine through the ureter. "However, further studies are needed to clarify the dynamics of PAQR5 expression decline in ureteral obstruction or other types of CKD." (PMID 37553369, 2023). "Earlier, we proposed that the lack of progesterone effects in unilateral ureteral obstruction may be due to the decreased expression of PAQR5 in the kidney." (PMID 38542129, 2024).
adenomyosis (1 paper, 2022). The growth of endometrial tissue inside the muscular wall of the uterine corpus. "No significant upregulation of PAQR5 was observed in adenomyosis compared to normal myometrium." (PMID 35956024, 2022).
breast invasive carcinoma (1 paper, 2022). "The results reveal that PAQR5 is overexpressed in liver hepatocellular carcinoma, cholangiocarcinoma, and breast invasive carcinoma." (PMID 36119517, 2022).
clear cell carcinomas (1 paper, 2022). "It has been reported that PAQR5 expression was significantly increased in endometrial and clear cell carcinomas, and expression in normal-cycle human endometrium varies in parallel with progesterone levels." (PMID 36119517, 2022).
hepatocellular carcinoma (1 paper, 2025). A malignant tumor that arises from hepatocytes. "Progesterone and adipose Q receptor 5 (PAQR5), a membrane receptor characterized by seven transmembrane domains, has been indirectly implicated in pro-carcinogenic activities, though its specific role in hepatocellular carcinoma (HCC) remains to be defined." (PMID 40336138, 2025). "However, the oncogenic potential and prognostic implications of PAQR5 in hepatocellular carcinoma have yet to be explored." (PMID 40336138, 2025).
osteoarthritis (1 paper, 2025). A noninflammatory degenerative joint disease occurring chiefly in older persons, characterized by degeneration of the articular cartilage, hypertrophy of bone at the margins and changes in the synovial membrane. "GSEA using the MSigDB database demonstrated that the GJB2, PAQR5 and CLEC12A genes activate inflammatory-related signaling (NES > 0) and suppress the cholesterol homeostasis (NES < 0), revealing their role in the meniscal degradation process during osteoarthritis progression." (PMID 40724902, 2025).
psychosis (1 paper, 2019). "Finally, Dbp, Paqr5, Ptprb, and Tmc7 are involved in the regulation of circadian rhythm, progesterone signaling, repression of EGFR signaling pathways, and psychosis risk, respectively." (PMID 31164799, 2019).
renal fibrosis (1 paper, 2023). A final common manifestation of a wide variety of chronic kidney diseases characterized by glomerulosclerosis and tubulointerstitial fibrosis. "In this study, we found a dramatic decrease in PAQR5 expression associated with renal fibrosis indicating a possible violation in progesterone signaling." (PMID 37553369, 2023). "Thus, we demonstrate for the first time diminished sensitivity of the kidney to progesterone associated with renal fibrosis due to a severe decrease in PAQR5 expression that was accompanied by the lack of nephroprotection in a rat UUO model." (PMID 37553369, 2023).
cancer (6 papers, 2011 to 2025). A tumor composed of atypical neoplastic, often pleomorphic cells that invade other tissues. "Given the critical role of immunomodulatory molecules in cancer immunotherapy, the association between these molecules and PAQR5 expression was examined to construct a comprehensive immune landscape related to PAQR5." (PMID 40336138, 2025). "PAQR5 downregulation was associated with tumor progression, including tumor stage, cancer grade, lymph node invasion, and distal metastasis." (PMID 35127538, 2021). "The association with the endoplasmic reticulum implies that PAQR5 may also be involved in protein folding and stress response mechanisms, which are frequently dysregulated in cancer." (PMID 40336138, 2025). "Nevertheless, further research is required to clarify the mechanisms driving PAQR5 expression and its functional impact on cancer progression." (PMID 40336138, 2025). "Previous studies reported the involvement of PAQR5 in cancer cell biology, but its role in musculoskeletal tissues and diseases remains to be further explored." (PMID 40724902, 2025). "Gene Set Variation Analysis (GSVA) was performed to assess the relationship between PAQR5 expression and cancer-related phenotypes." (PMID 40336138, 2025). "It was found that critical molecules involved in the NF-κB pathway, including ERK and p65, were significantly co-activated with PAQR5 in malignant tumor cells." (PMID 40336138, 2025). "PAQR5 expression showed a significant decreasing trend in cancer stages, with the lowest expression in Stage 4 compared with that in Stage 1 (P < 0.001)." (PMID 36119517, 2022). "Here, we investigated the correlation of PAQR5 expression with cancer stage, tumor grade, nodal metastasis status, subtype, age, and gender using the UALCAN database on a KIRC dataset derived from TCGA." (PMID 36119517, 2022). "In contrast, PAQR5 protein was only expressed in stromal cells of ccRCC tissues and were almost lost in cancer cells." (PMID 35127538, 2021). "PAQR5 downregulation correlated with tumor stage, cancer grade, lymph node invasion, and distal metastasis only in clear cell RCC (ccRCC) tissues." (PMID 35127538, 2021). "Since promoter hypermethylation is one of the central mechanisms for gene silencing in human cancers, we analyzed the methylation levels of PAQR5 gene promoters based on the TCGA data." (PMID 35127538, 2021). "As seen in the PPI network, PAQR5 may influence cancer development through interactions with AERG and HRAS." (PMID 36119517, 2022). "In addition, downregulation of PAQR5 is strongly coupled with higher cancer stages, higher histological grade, metastasis, and a malignant subtype of KIRC." (PMID 36119517, 2022). "TGFβ1 treatment in human cancer cells significantly suppressed PAQR5 expression." (PMID 35127538, 2021). "However, PAQR5 expression correlated considerably with all pathological and clinical parameters, including tumor stage, cancer grade, lymph node invasion, distal metastasis, disease relapse, and survival outcomes only in ccRCC but not in pRCC or ChRCC." (PMID 35127538, 2021). "DNA methylation analysis indicated that PAQR5 promoter methylation in ccRCC tissues was significantly higher than in normal kidney tissues and correlated with tumor stage and cancer grade in ccRCC tissues, indicating that DNA methylation could be a potential mechanism for PAQR5 downregulation." (PMID 35127538, 2021). "Beyond the well-studied genes, our data indicated the potential roles of several other genes, including PAQR5, TRIM16, and ZC3H12A, in modulating cancer cell behavior." (PMID 37958599, 2023). "PAQR5 expression was low in KIRC and correlated significantly with clinical characteristics including cancer stage, tumor grade, and nodal metastasis status." (PMID 36119517, 2022).
tumor (5 papers, 2021 to 2025). "Single variant logistics analysis revealed that aberrant expression of PAQR5/6 genes was a significant risk factor for tumor stage progression and lymph node invasion." (PMID 34572596, 2021). "Furthermore, IHC staining and western blot analysis verified less PD-L1 expression and FOXP3 + Treg cells but more CD8 + cells in mice tumor tissue caused by PAQR5 knockdown (P < 0.01)." (PMID 40336138, 2025). "Tregs, known for their role in immune escape, are associated with poor clinical outcomes, suggesting that PAQR5 may contribute to an immunosuppressive microenvironment that fosters tumor growth." (PMID 40336138, 2025). "Although both PAQR6 upregulation and PAQR5 downregulation were significantly correlated with tumor pathological stages, only PAQR6 upregulation was associated with Gleason score, free-prostate-specific antigen (fPSA)/total-PSA (tPSA) ratio, and patient overall survival outcomes." (PMID 34572596, 2021). "Spatial transcriptomics further corroborated the alignment of PAQR5 expression with tumor cell distribution." (PMID 40336138, 2025). "In vivo analysis of these subcutaneous xenografts confirmed the in vitro findings, showing that PAQR5 knockdown significantly inhibited tumor growth compared to the vehicle control group (P < 0.05)." (PMID 40336138, 2025). "The UMAP plot highlights significant PAQR5 expression predominantly in malignant tumor cells and M1 macrophages." (PMID 40336138, 2025). "This study also explored the relationship between PAQR5 expression and the tumor immune microenvironment, utilizing functional enrichment analyses to identify potential mechanistic pathways." (PMID 40336138, 2025). "In investigating the relationship between PAQR5 expression, immune infiltration, functional enrichment, and tumor phenotype in HCC, this study employed multiple levels of validation, including spatial transcriptomics and ex vivo experiments." (PMID 40336138, 2025). "Across all three samples (HCC1, HCC2, HCC3), PAQR5 expression was spatially consistent with the distribution of tumor cells, indicating a predominant expression in the malignant regions." (PMID 40336138, 2025). "In vivo studies demonstrated that targeting PAQR5 attenuated tumorigenic potential, disrupted the invasion-metastasis cascade and inhibited the tumor immune escape." (PMID 40336138, 2025). "PAQR5 expression was significantly upregulated in tumor tissues and correlated with poor clinical outcomes." (PMID 40336138, 2025). "Immunohistochemical staining demonstrated that tumor tissues from the PAQR5 knockdown group exhibited reduced Ki-67 and vimentin expression, alongside increased E-cadherin staining, compared to controls (P < 0.05)." (PMID 40336138, 2025). "First, we compared PAQR5 expression in tumor and paracancerous tissues in the TCGA pancancer dataset using the Wilcoxon rank sum test." (PMID 36119517, 2022). "We also explored the relevance of PAQR5 to tumor immune cell infiltration and immunomodulatory molecules by TIMER and GEPIA." (PMID 36119517, 2022). "Then, we compared PAQR5 expression in 72 normal paracancerous tissues and 539 tumor tissues in the KIRC TCGA dataset." (PMID 36119517, 2022). "We examined the expression of PAQR5 protein in tumor and normal tissues adjacent to the tumor by immunohistochemistry (IHC)." (PMID 36119517, 2022). "Overall, in KIRC with low PAQR5 expression, tumor-infiltrating immune cells are generally in a state of immunosuppression." (PMID 36119517, 2022). "Its correlation with apoptosis and DNA damage/repair processes implies that PAQR5 could affect cell survival and genomic stability, thereby promoting tumor progression." (PMID 40336138, 2025). "Additionally, genetic causal variation between PAQR5 and HCC was identified, further implicating PAQR5 in tumor development." (PMID 40336138, 2025). "Evidently, PAQR5 deletion or low expression may promote tumor development through the JAK/STAT signaling pathway activation." (PMID 36119517, 2022).
tumor (continued). "Through GSEA enrichment analysis, we also observed that low PAQR5 gene expression was associated with upregulation of STAT3 targeting, downregulation of tumor metastasis, upregulation of tumor formation, poorer tumor differentiation, and downregulation of the NRAS signaling pathway." (PMID 36119517, 2022). "PAQR5 was also significantly downregulated in tumor tissues in 72 pairs of KIRC samples." (PMID 36119517, 2022). "Moreover, immunohistochemistry was performed to observe the expressions of PAQR5 protein in tumor tissues." (PMID 36119517, 2022). "We examined the correlation between PAQR5 expression and the degree of infiltration of six immune cell subtypes (CD8+ T cells, CD4+ T cells, B cells, DCs, macrophages, and neutrophils) by TIMER and its association with tumor purity." (PMID 36119517, 2022). "In ChRCC patients, PAQR5 expression was only significantly associated with tumor stage but not with other parameters." (PMID 35127538, 2021). "Analysis of methylation levels in the 5’ untranslated region (5’ UTR) of PAQR5 revealed significantly higher methylation in normal tissues compared to tumor tissues, suggesting that hypermethylation may contribute to PAQR5 silencing and reduced expression in normal cells." (PMID 40336138, 2025). "In our current research, we first reported that low expression of PAQR5 was related to various adverse events in KIRC, including poor survival, poor prognosis, tumor progression, and tumor immunosuppression." (PMID 36119517, 2022). "The comprehensive multi-omics analysis and experimental findings delineate a potential oncogenic role for PAQR5 in HCC via modulation of the NF-κB pathway, highlighting its relevance in promoting malignant cell behavior and establishing an immunosuppressive tumor microenvironment." (PMID 40336138, 2025). "The results revealed that the downregulation of PAQR5 enriched mainly the gene set related to the upregulation of STAT3 targets, tumor formation, and poor tumor differentiation and enriched the gene set of downregulated tumor metastasis and NRAS signaling." (PMID 36119517, 2022). "More than half of the tumor samples (n = 49, 58.3%) did not express PAQR5 protein or just low expression compared with those highly expressed (n = 35, 41.7%)." (PMID 36119517, 2022). "However, unlike PAQR5, PGR and PGRMC1 downregulation were not consistently associated with tumor progression in TNM categories, lymph node invasion, and distal metastasis." (PMID 34572596, 2021).
PAQR5 also shares sentences with these, for which no sentence is quoted: glioblastoma (2 papers); ovarian carcinoma (2); cholangiocarcinoma (1); colon adenocarcinoma (1); colorectal cancer (1); esophageal adenocarcinoma (1); esophageal carcinoma (1); kidney chromophobe (1); lung adenocarcinoma (1); pancreatic cancer (1); paraganglioma (1); pheochromocytoma (1); prostate adenocarcinoma (1); rectal adenocarcinoma (1); Renal Clear Cell Carcinoma (1); thyroid carcinoma (1); viral infection (1).